GAPDH (glyceraldehyde-3-phosphate dehydrogenase)
Diseases named in the same sentence as GAPDH in open-access papers (continued):
Sharing a sentence is not in itself a finding about the gene and the disease.
infection (continued). "The ratio of LC3II/GAPDH showed an increasing trend by Western blotting, and the protein expression level of SQSTM1/p62 presented a similar trend after 4 h of infection." (PMID 32431700, 2020). "Phenotypic measures including transcript levels for the fungal genes glyceraldehyde 3-phosphate dehydrogenase (Fg-GAPDH) and β-tubulin (Fg-βTUB) and DON concentration revealed a broad range of infection levels among DH lines derived from Wuhan 1 and Nyubai." (PMID 31795937, 2019). "The finding that Plasmodium surface-GAPDH is a sporozoite ligand for liver invasion prompted us to explore the possibility that an antibody against PbGAPDH may interfere with infection of mammals by preventing Kupffer cell traversal and subsequent infection of the liver." (PMID 30456380, 2018). "Consistent with this, there was a significant and dose-dependent increase in viperin mRNA levels in response to infection with both PR8 and WSN when normalized to 18S RNA as well as GAPDH and actin." (PMID 28769891, 2017). "As we previously reported with non-PNA-treated E. chaffeensis, based on the levels of E. chaffeensis 16S rRNA/human GAPDH mRNA, Etf-1-GFP-transfection of HEK293 cells enhanced infection of CTL PNA-treated E. chaffeensis compared to the GFP-transfection CTL." (PMID 28638803, 2017). "Prominently, we observed that the relative mRNA level of BS69 over Glyceraldehyde 3-phosphate dehydrogenase (GAPDH) in primary B cells was significantly decreased following EBV infection, with a >20-fold reduction at day 5 post-infection." (PMID 26845565, 2016). "For barley, GAPDH, UBI and TUBA2B were the three most stable RNAs during infection, and ACT was the least stable of the control RNAs (in contrast with B. graminis, where ACT was one of the two most stable RNAs)." (PMID 26238194, 2016). "Depletion of host FNR transcripts during infection in the light, and putative protein–protein docking between FNR and GAPDH in the Calvin cycle, point towards minimal NADPH production by PET." (PMID 27788196, 2016). "The B. graminis glyceraldehyde‐3‐phosphate dehydrogenase (GAPDH), actin (ACT) and histone 3 (H3) genes and the barley GAPDH, ubiquitin (UBI) and α‐tubulin 2B (TUBA2B) genes were optimal normalization controls for qPCR during the infection cycle." (PMID 26238194, 2016). "The conidia‐specific gene was found to decrease in abundance in both epidermal and epiphytic material following infection, when normalized against the best (ACT, GAPDH and H3) or worst (TUB2B) control genes." (PMID 26238194, 2016). "In this study, the expression change of IgM gene was investigated in parallel with six candidate reference genes including 18S rRNA, ACTB, TUBA, UBCE, GAPDH and EF1A during vaccination with vaccine and infection with bacteria in spleen of Nile tilapia." (PMID 25941937, 2015). "A non-targeting (NT control) was used as a control for the experiment and DENV1 genome copies relative to GAPDH were measured by RTPCR at 24 and 48 hours post infection." (PMID 26327586, 2015). "We prepared BMDMs and DCs followed by infection with LM-WT (bacteria: cells ratio, 10:1) (BMDM-LM-WT or DC-LM-WT) or loaded with 50 μM purified LLO (BMDM-LLO or DC-LLO) or GAPDH (BMDM-GAPDH or DC-GAPDH) for 16 h." (PMID 24600592, 2014). "We determined the mRNA expression levels of several housekeeping genes (GAPDH, B2M, HPRT1) to examine the effect of infection with H6R28LEP on PBMCs." (PMID 23409116, 2013). "Taken together, these results demonstrate the role played by the early secretory pathway, in particular the GAPDH/COPI/Rab2/PKCι/λ retrograde vesicles, to ensure replication within host cells at late stages of infection." (PMID 19557163, 2009). "The merged images showed that GAPDH and NS5 protein colocalized in the cytoplasm throughout the infection period and in the nucleus of a few cells at 24 hpi." (PMID 19368702, 2009).
infection (continued). "The convergent evidence from multiple algorithms underscores the reliability of selecting GAPDH and TUBA as the reference gene pair for qPCR normalization in gene expression studies targeting the 18–23 days post-infection developmental window of female Schistosoma japonicum." (PMID 41156676, 2025). "GAPDH mRNA was prevalently localised in the cytoplasm irrespective of infection, thus validating the sub cellular fractionation procedure." (PMID 41474797, 2025). "Nonetheless, the normalization with GAPDH as a reference gene produced a high-NRF2–high-IL-6 expression phenotype as both IL-6 and NRF2 showed massive induction (>400-fold) in patients with mild infection and in pre- and post-CAM patients." (PMID 36377893, 2022). "Importantly, the decrease in DAXX protein levels is likely not attributed to a global host protein expression shut down, as the levels of Lamin B, HSP90, Actin, GAPDH, Tubulin, TRIM22 and RIG-I were unchanged upon infection." (PMID 35508460, 2022). "Although the Lys306Arg substitution found in 13 of the MS-H reisolates is not in the NAD-binding domain of GAPDH, this frequent reversion to the wild-type C-terminal seems to be beneficial for infection." (PMID 36318012, 2022). "Infected Vero cells were collected 20 h post-infection, and total cell lysate was subjected to western blot analysis using antibodies directed against HSV-1 infected cellular protein 0 (ICP0), glycoprotein D (gD), thymidine kinase (TK), and GAPDH." (PMID 33435520, 2021). "In fact, the preceding infection might be an infection other than GAS, because the GAPDH of various bacteria show cross-immunoreactivity to the anti-NAPlr antibody, and simultaneously show plasmin-binding function." (PMID 33477598, 2021). "In conclusion, GAPDH and YWHAZ could be used as reference genes for the normalisation of chicken IEL-NK cell gene responses to infection with vvIBDV." (PMID 32444639, 2020). "At different times post-infection, levels of IFN-β and GAPDH transcripts were quantified by qPCR." (PMID 32486154, 2020). "The merged images revealed that the GAPDH and NS3 proteins colocalized in these regions in DENV2-infected cells at 48 h post-infection, suggesting that GAPDH localization might be modulated upon DENV2 infection." (PMID 30804377, 2019). "However, as the time of infection proceeds, this regulation turns to be controlled by the NS3 protein, decreasing the GAPDH activity." (PMID 30804377, 2019). "GAPDH was chosen as reference gene since its expression did not change significantly following infection." (PMID 30036391, 2018). "Consistent with the absence of putative CTCF-binding sites, CTCF was not enriched at the LAT promoter (LAP) or at the cellular GAPDH pseudogene relative to the nonspecific antibody control upon infection with either ΔCTRL2 or CTRL2R virus." (PMID 29437926, 2018). "WSN mRNA levels were normalized to GAPDH (glyceraldehyde-3-phosphate dehydrogenase) in each sample, and relative infection levels were normalized to the nontargeting siRNA (siNT)." (PMID 30429226, 2018). "When immunostaining for GAPDH, weak signals were seen for MAdV-1 and -3 only at 48 h post infection Staining for actin and tubulin showed similar results (not shown), in agreement with the reduced levels of cellular proteins." (PMID 28821267, 2017). "The silencing efficiency of H1C was detected using real-time PCR, and it showed that H1C was specifically silenced during infection; the Si-NC and Si-GAPDH groups were served as negative or positive controls." (PMID 28392790, 2017). "Previous studies assessing gene expression changes as a consequence of infection in mallards have nearly universally used β-actin and/or GAPDH as reference genes without confirming their suitability as normalisers." (PMID 26886224, 2016).
infection (continued). "After normalizing to endogenous GAPDH gene expression, FXN expression in the human and mouse FRDA cells reached 96- and 210-fold, respectively, after infection, compared with uninfected FRDA cells 0.5- and 0.2-fold, respectively, compared with normal fibroblasts." (PMID 27518705, 2016). "In the context of mock infection or HCV infection, BiP, a chaperone located in the lumen of the ER, and GAPDH, a cytosolic protein, were predominantly fractionated into fractions 8 and 9 and fractions 15 to 22, representing the ER/endosome and soluble/aggregated protein fractions, respectively." (PMID 27489281, 2016). "GAPDH-RNAi was used as a positive control of optimal infection conditions for the cell lines and a non-targeting shRNA sequence within the lentiviral vector was used as negative control." (PMID 27502396, 2016). "As controls, the levels of GAPDH expression were similar in all samples (data not shown), and the levels of viral gene M were similar after infection with virus r85." (PMID 27535054, 2016). "We could identify reference genes that are suitable for expression profiling during the infection process in planta and combined with the germ tube stage: CytB/PDK or CytB/GAPDH and Elf3/RPS9 or PKD/GAPDH are suitable reference gene combinations." (PMID 26404265, 2015). "RT-qPCRs conducted for the assessment of β-Actin- and GAPDH as reference targets (see section 2.4) revealed no coherent changes in expression levels after different stimulation or infection and thus, suitability for gene expression normalization was confirmed." (PMID 25268123, 2014). "V6 expression was reduced after G9 and G11 shRNA infection as shown by the V6/GAPDH ratio, whereas G10 shRNA infection did not induce the alteration of V6 expression significantly." (PMID 24173428, 2014). "1.5 hours after infection cells were harvested and lysates were analysed by immunoblotting with caspase-1, -9, -7, poly (ADP-ribose) polymerase (PARP), and glycerinaldehyde 3-phosphate dehydrogenase (GAPDH) antibodies." (PMID 24626296, 2014). "Negative siRNA controls (GAPDH and scrambled construct) had no significant impact on infection and are included for comparison purposes." (PMID 24809507, 2014). "In conclusion, RPL30 and SDHA could be used as reference genes for the standardization of in CEF gene response to the infection with ALV-J, whereas commonly used ACTB and GAPDH are unsuitable to be reference genes in ALV-J/CEF settings." (PMID 24099561, 2013). "According to BestKeeper and Normfinder, ATP synthase β, tropomyosin and GAPDH were the most stable genes upon time and infection, but, according to geNorm, none of the candidate genes was acceptable as reference upon the entire experimental period." (PMID 24119747, 2013). "The levels of GAPDH mRNA were not significantly altered with the addition of the histone siRNA, indicating that cell health was not the reason for reduced infection." (PMID 21909430, 2011). "Therefore, for the rose, we propose the use of PP2A, UBC (and GAPDH) for the expression analysis of different tissues and SAND, UBC (and TIP) for the analysis of stress treatments such as wounding, heat stress and infection by pathogens." (PMID 22123042, 2011). "In contrast, by infection with JEV, the nuclear-GAPDH appeared to be localized to the cytoplasm." (PMID 19368702, 2009). "We observed a dramatic reduction (∼80 fold) of UIS4 transcript abundance in slarp(-) parasites as compared to WT parasites 6 hours post-infection, while control transcripts for GAPDH and heat shock protein 70 (HSP70) were not affected." (PMID 18551171, 2008). "However, as observed earlier by us and others, the regulation of poly-A termination of some genes (such as histones, GAPDH, and others, data not shown) seems not to be affected by the infection with mutant or wild-type IAV." (PMID 40442346, 2025).
infection (continued). "The M. bovis glyceraldehyde-3-phosphate dehydrogenase (GAPDH) protein was assessed as a potential vaccine antigen after it was discovered that calves produced antibodies against GAPDH following infection though this protein did not provide protection to vaccinated calves in challenge studies." (PMID 38988984, 2024). "Control GAPDH transcript was not significantly affected by Tg treatment or infection." (PMID 38399988, 2024). "Indeed, simulated concentrations of the glycolytic metabolites G6-P and 1,3BPG, generated by HK and GAPDH reactions, respectively, plus rate of production of lactate and ATP production from glycolytic PGK are highly upregulated upon infection and return to basal levels during the recovery phase." (PMID 37679643, 2023). "GAPDH was used as a house-keeping gene, which displayed a non-coherent expression likely due to either the heterogeneous cell population found in the CP tissue or lower RNA integrities compared to RNA from the in vitro infection experiments." (PMID 33763387, 2021). "The subcellular localization of GAPDH does not change during infection with BaMV or satBaMV." (PMID 33920930, 2021). "Thus, GAPDH and YWHAZ could be used as reference genes for the normalisation of chicken IEL-NK cell gene response following infection with vvIBDV, whereas the commonly used ACTB is unsuitable to be used as a reference gene in IEL-NK cells infected with vvIBDV." (PMID 32444639, 2020). "In this study, we selected six commonly used endogenous controls including 18S rRNA, ACTB, TUBA, UBCE, GAPDH and EF1A as candidate reference genes for normalizing the expression levels of immune-related gene IgM and analyzed their expression stabilities during vaccination and infection in tilapia." (PMID 25941937, 2015). "It should be noted that we did not observe a dramatic decrease in GAPDH mRNA levels throughout the infection, although we did observe a slight drop (approximately equal to one Ct) very late in the infection (96 hours and later for dl309 and pm975, even later for dl520)." (PMID 26448631, 2015). "GAPDH was constitutively expressed in both cell lines and expression did not vary by infection." (PMID 25013817, 2014). "The recognition of GAPDH by pathogens have been associate with quite uptake, and supports the hypothesis that MAP needs to invade the mucosa of the intestine without facing phagocytic cells, until the infection become established." (PMID 29998085, 2018). "Finally, no significant modification of cellular GAPDH expression levels, determined by RT-qPCR, was observed at 4 h after infection while a slight decrease was observed at 9 h during wild type VACV or VACVΔB18 infection in either the absence or presence of IFN." (PMID 28280747, 2017). "Thus, a mammalian recombinant GAPDH obtained from Sigma was used to produce a standard curve, which then was used to determine the amount of GAPDH in uninfected and infected lungs at day 6, 12 and 18 days post infection (data not shown)." (PMID 21203393, 2010). "Using these constructs to determine effects of infection on amyloidogenic versus non-amyloidogenic pathways, we first co-transfected HEK293A cells with GAPDH control, Flag-C99 or Flag-C83 together with increasing amounts of HIV-1 JR-CSF." (PMID 37454116, 2023). "We detected a strong association of NEIL2 with full length SARS-CoV-2 5’-UTR RNA, mimicking the in vivo post infection CoV-2 RNA-NEIL2 interactions, but not with the 5’-UTR RNA of several host genes; GAPDH, HPRT and DNA polymerase β (POLB) as controls." (PMID 38071370, 2023). "GAPDH mRNA was successfully pulled-down with MOV10 from both HBV-infected samples and the no-infection controls." (PMID 31319455, 2019). "The ratio of MHC I to GAPDH mRNA in non-infected cells ranged between 0.63 and 0.65 (Lanes 2 and 4), which remained almost unaltered 10 or 24 h after ORFV infection (lanes 1 and 3)." (PMID 22809544, 2012).
infection (continued). "In a MRC-5 lytic infection model, transient transfection with two individual JMJD3 siRNAs led to reduced accumulation of hCMV IE mRNAs (IE1 and Us3) and IE1 protein, but not cellular controls GAPDH and Sp1." (PMID 28407004, 2017). "Interestingly, we find that Schlafen11 is functional in the absence of infection and reduces protein production from certain non-viral (GFP) and even host (Vinculin and GAPDH) transcripts." (PMID 28027315, 2016). "In addition, the infection with both viruses did not affect the protein expression of p85, SHP2, and GAPDH." (PMID 26090437, 2015).